DIP2C-AS1 (DIP2C antisense RNA 1)
Synonyms: C10orf108; PRR26; FLJ38681
Gene: Long non-coding RNA gene on chromosome 10 (649,948 to 669,581, forward strand). Ensembl gene ENSG00000180525.
Diseases named in the same sentence as DIP2C-AS1 in open-access papers:
DIP2C-AS1 is named in the same sentence as 1 disease in open-access papers, as found by Europe PMC text mining. Sharing a sentence is not in itself a finding about the gene and the disease.
DIP2C-AS1 shares sentences with these, for which no sentence is quoted: malignant tumors (1 paper).